LINC01720 (long independently transcribed non-coding RNA 1720)
Gene: Long non-coding RNA gene on chromosome 1 (190,624,890 to 190,801,658, forward strand). Ensembl gene ENSG00000231175.
Diseases named in the same sentence as LINC01720 in open-access papers:
LINC01720 is named in the same sentence as 1 disease in open-access papers, as found by Europe PMC text mining. Sharing a sentence is not in itself a finding about the gene and the disease.
LINC01720 shares sentences with these, for which no sentence is quoted: schizophrenia (1 paper).